SNORD69 (small nucleolar RNA, C/D box 69)
Synonyms: HBII-210
Gene: Small nucleolar RNA gene on chromosome 3 (52,692,736 to 52,692,812, forward strand). Ensembl gene ENSG00000212452.
Gene Ontology:
Biological process: RNA processing
Cellular component: nucleolus
Homologues: Orthologues: chimpanzee SNORD69 (100% identical), macaque SNORD69 (99% identical), rabbit SNORD69 (94% identical), guinea pig SNORD69 (91% identical), mouse Snord69 (88% identical), rat Snord69 (87% identical), pig SNORD69 (86% identical).